HGF (hepatocyte growth factor)
Diseases named in the same sentence as HGF in open-access papers (continued):
Sharing a sentence is not in itself a finding about the gene and the disease.
chordoma (5 papers, 2014 to 2025). Chordomas are rare malignant tumors arising from embryonic remnants of the notochord in axial skeleton. "The receptor tyrosine kinase MET and its ligand hepatocyte growth factor are strongly expressed in primary chordoma samples, and chordoma cell lines, particularly of sacral origin, are sensitive to MET inhibition." (PMID 40901948, 2025). "In summary, upon stimulation with HGF, the cMET inhibitors crizotinib and cabozantinib had a significantly stronger effect on protein phosphorylation in sacral chordoma cell lines compared to clival ones." (PMID 34127734, 2021). "MUG-CC1 showed the lowest cMET signal (-HGF: 0.03 ± 0.02 vs + HGF: 0.02 ± 0.01) compared to the other tested chordoma cell lines." (PMID 34127734, 2021). "We found that HGF distinctly enhanced the migration of two sacral chordoma cell lines MUG-Chor1 and U-CH2 cells, moderately attracted the clival UM-Chor1 cells, and did not affect MUG-CC1 cells." (PMID 34127734, 2021). "We found that sacral chordoma cell lines showed a stronger migration towards an HGF-gradient compared to clival cell lines." (PMID 34127734, 2021). "To assess the role of HGF on chordoma cell migration, we studied the cell lines ́ migration behaviour upon stimulation with HGF using the real-time xCELLigence system." (PMID 34127734, 2021). "Comparing chordoma cell lines after HGF stimulation, U-CH2 showed the strongest phospho-cMET—which is the activated form of cMET-expression, and MUG-CC1 the lowest." (PMID 34127734, 2021). "Stimulation with 10 ng/ml HGF for 1 h lead to a significant increase of cell viability in chordoma cells after 72 h." (PMID 34127734, 2021). "The expression of the cytokines was used to functionally demonstrate that the cMET/HGF axis is active in all chordoma cells." (PMID 34127734, 2021). "Cell migration and chemotaxis towards an HGF gradient have been described previously in the chordoma cell line CCL316." (PMID 34127734, 2021). "Moderate and strong expression of membrane and cytoplasmic cMET in chordoma patients and cell lines used, as well as concentration-dependent increase in phospho cMET expression after HGF stimulation in all four chordoma cell lines was shown." (PMID 34127734, 2021). "Our viability data clearly showed that, after HGF-stimulation, sacral chordoma cell lines responded better to treatment with cMET inhibitors than clival cell lines." (PMID 34127734, 2021). "We analysed the protein expression of cMET and phospho-cMET under HGF stimulation in all four chordoma cell lines by western blot analysis." (PMID 34127734, 2021). "Among other growth factors, we investigated HGF expression at the beginning of culture where TSC as well as chordoma cells were present." (PMID 27072875, 2016). "Pronounced expression of HGF and cMET was found in skull base chordomas." (PMID 27072875, 2016). "Overexpression of MET and HGF in chordoma enhances cell survival and invasion." (PMID 24621885, 2014). "Two clival and two sacral chordoma cell lines were tested for chromosomal abnormalities of the MET gene locus; we studied the influence of HGF on the autocrine secretion and migration behavior, as well as protein expression and phosphorylation." (PMID 34127734, 2021). "As the majority of chordomas express cMET and its ligand, HGF, and crosstalks between EGFR and MET-signaling exist, we aimed to explore cMET activity in chordoma cell lines and clinical samples." (PMID 34127734, 2021). "During cultivation, there was significant expression of HGF and SDF-1 compared to continuous chordoma cell lines." (PMID 27072875, 2016). "We detected a time-dependent (24–72 hours) significant increase of HGF in TSC, especially as MUG-CC1 was becoming established, compared to stable chordoma cell lines and fibroblasts." (PMID 27072875, 2016).
chordoma (continued). "The receptor tyrosine kinase MET and its ligand hepatocyte growth factor (HGF) are expressed in a variety of solid tumors, including chordomas and have emerged as key determinants of tumor growth and invasion." (PMID 24621885, 2014). "We activated EGFR with EGF (20 ng/ml) or MET with HGF (20 ng/ml) treatment in UCH1 and C24 chordoma cells." (PMID 24621885, 2014). "Because connective tissue cells were visible during cultivation, we measured HGF, FGF2, SDF-1, and PDGF compared to stable chordoma cell lines (MUG-Chor118 and U-CH1-319) and healthy normal skin fibroblasts (fibro), as well as tumor-surrounding cancer cells (TSC)." (PMID 27072875, 2016).
diabetic neuropathy (5 papers, 2018 to 2022). A chronic, pathological complication associated with diabetes mellitus, where nerve damages are incurred due to diabetic microvascular injury involving small blood vessels that supply these nerves, resulting in peripheral and/or autonomic nerve dysfunction. "Clinically, intramuscular administration of VM202, plasmid DNA expressing two isoforms of HGF, resulted in significant symptomatic relief in painful diabetic neuropathy." (PMID 32780756, 2020). "In a double-blind, placebo-controlled study, Kessler at al. confirmed that repeated intramuscular injections of HGF are effective in reducing pain in patients with painful diabetic neuropathy." (PMID 32780756, 2020). "It is interesting to note that in patients taking calcium channel blockers such as pregabalin and/or gabapentin used as first-line treatments for diabetic neuropathy, the pain-reducing effect of plasmid DNA designed to express human HGF was significantly reduced in clinical trials." (PMID 33718632, 2021). "HGF is also a good candidate to be one of the factors facilitating CM-induced therapeutic effects on neuropathy because of its powerful angiogenetic and neurotrophic actions and its clinical therapeutic effects in patients with painful diabetic neuropathy." (PMID 29535781, 2018). "Thus, HGF alone (even when delivered in two isoforms) may fail to reduce diabetic neuropathy, and beneficial effects of VEGF165 may provide additional therapeutic impact to overcome this hurdle." (PMID 33353116, 2020). "VM202 is a plasmid carrying two isoforms of HGF with 728 (HGF728) and 723 (HGF723) amino acid residues intended for the treatment of cardiovascular diseases and painful diabetic neuropathy." (PMID 33353116, 2020).
esophageal cancer (5 papers, 2015 to 2021). A primary or metastatic malignant neoplasm involving the esophagus. "Several genes/pathways have been implicated to esophageal cancer migration, such as Cdc42, HGF/SF, Androgen receptor, RhoA, Rac-1, and Cdc42, VEGF, HER2, PLCE1, ABCG2/V-ATPase, MMS19." (PMID 28147311, 2017). "Two angiogenic factors (HGF and Follistatin) in posttherapeutic tumor tissue are associated with prognosis in esophageal cancer patients." (PMID 25885021, 2015). "Of the angiogenic factors VEGF, Angiopoietin-2, PECAM-1, Follistatin, Leptin, G-CSF, HGF, PDGF-BB and IL-8, two angiogenic factors (HGF and Follistatin) are associated with esophageal cancer patients’ prognosis in posttherapeutic tumor tissue." (PMID 25885021, 2015). "In this study two angiogenic factors (HGF and Follistatin) in tumor tissue after neoadjuvant therapy were associated with esophageal cancer patients’ prognosis." (PMID 25885021, 2015). "HGF levels seem to be important with regard to tumor development in esophageal cancer." (PMID 25885021, 2015). "Regarding the postoperative serum HGF levels, we showed that patients with high HGF levels on POD 3 had poorer overall survival than those with low HGF levels, suggesting that enhanced postoperative HGF levels are associated with tumor progression in esophageal cancer." (PMID 32630328, 2020). "In fact, previous studies have suggested that HGF promotes invasion of ESCC cells and FGF7 (keratinocyte growth factor: KGF) increases the growth rate of esophageal cancer cell lines (TE-8 and TE-11)." (PMID 25884729, 2015). "Other pro-angiogenic factors such as HGF, FGF and IL-8 have been reported to play a role in esophageal cancer." (PMID 25885021, 2015).
Hyperinsulinemia (5 papers, 2013 to 2024). An increased concentration of insulin in the blood. "Further support, for HGF being utilized as a therapeutic target in the treatment of IR, comes from its role in β-cell hyperplasia, and subsequent hyperinsulinemia." (PMID 30214428, 2018). "In experimental studies, investigators demonstrated that HGF plays a key role in pancreatic islet cell mass increase (and hyperinsulinemia), and insulin signaling in the liver." (PMID 27158627, 2015). "Hyperinsulinemia upregulates the production of insulin-like growth factor-1 and hepatocyte growth factor (HGF), leading to HCC progression." (PMID 24978432, 2014).
hyperopia (5 papers, 2011 to 2019). A refractive error in which rays of light entering the eye parallel to the optic axis are brought to a focus behind the retina, as a result of the eyeball being too short from front to back. "We selected HGF gene SNP rs12536657 that was previously reported as associated with hyperopia in an Australian adult population." (PMID 30863626, 2019). "Here, we assess the association of an HGF gene variant, previously reported as associated with hyperopia, and ocular biometric parameters in a multicenter Spanish cohort." (PMID 30863626, 2019). "Recent studies have found that some SNPs of the HGF gene were associated with susceptibility to hyperopia." (PMID 23585864, 2013). "Hepatocyte growth factor (HGF) was thought to play an important role in the emmetropization process of the eye, and several single nucleotide polymorphisms (SNPs) of the HGF gene were firstly reported to be associated with hyperopia." (PMID 23585864, 2013). "We selected rs17427817, rs5745718, and rs3735520 as the candidate SNPs based on the fact that these SNPs in the HGF gene were reported to be associated with hyperopia in the Chinese Han population and PACG in other populations." (PMID 23585864, 2013). "The authors identified two single nucleotide polymorphisms (SNPs; rs12536657 and rs5745718) within HGF that were significantly associated with hyperopia." (PMID 21897747, 2011). "In addition, the HGF gene has been found to be associated not only with hyperopia but also with corneal pathology in several studies." (PMID 30863626, 2019). "The first positive genetic association for hyperopia was published in 2010 when the association of SNPs rs12536657 and rs5745718 of the HGF gene with hyperopia was reported in a case-control study of the Australian population comprising emmetropic, hyperopic, and myopic adult subjects." (PMID 30863626, 2019). "Furthermore, the membrane frizzled-related protein (MFRP) gene was related to nanophthalmos while the hepatocyte growth factor (HGF) gene was reported to be associated with hyperopia, and both nanophthalmos and hyperopia are important risk factors for PACG." (PMID 30348125, 2018). "A recent study found some SNPs of the HGF gene were associated with susceptibility to hyperopia." (PMID 30348125, 2018). "The polymorphisms of the HGF gene have been widely studied in hyperopia in different populations." (PMID 23585864, 2013). "As angle-closure glaucoma and hyperopia share the same feature of a short axial length, the HGF gene may be also a risk factor of PACG." (PMID 23585864, 2013). "On the other hand, our results did not support the association of this HGF gene SNP with hyperopia for the Spanish pediatric population." (PMID 30863626, 2019). "Although recent genome-wide association studies (GWAS) have focused on other genes related to refractive state and hyperopia, the association of the HGF gene with hyperopia has not been studied in other populations." (PMID 30863626, 2019).
Infertility (5 papers, 2018 to 2025). "The level of HGF was reported to be changed in a comparison between healthy and infertility individuals." (PMID 31752687, 2019). "There are suggestion that infertile women with RIF could benefit from the use of platelet-rich plasma (PRP) containing growth factors (PDGF, EGF, TGFβ, VEGF, HGF, FGF2)." (PMID 36901702, 2023).
influenza (5 papers, 2015 to 2025). An acute viral infection of the respiratory tract, occurring in isolated cases, in epidemics, or in pandemics; it is caused by serologically different strains of viruses (influenzaviruses) designated A, B, and C, has a 3-day incubation period, and usually lasts for 3 to 10 days. "Nevertheless, recombinant HGF stimulates alveolar proliferation and alveolar repair in the mouse during influenza infection and protects against alveolar damage." (PMID 26033355, 2015). "HGF levels in the lungs are increased in ARDS, and plasma concentrations of HGF are significantly increased in patients with severe influenza infection." (PMID 26033355, 2015). "HGF secretion by fibroblasts was stimulated by AEC production of prostaglandin E2 during influenza infection." (PMID 26033355, 2015). "For example, the EGFR inhibitor, AG1478, inhibits basal wound closure in human bronchial epithelial cells, and anti-HGF antibody added to mouse lung explants after influenza infection reduces alveolar epithelial regeneration." (PMID 26033355, 2015). "Determining the role of HGF in the mouse during influenza infection is, however, more complicated because murine alveolar macrophages express and secrete HGF, whereas human alveolar macrophages do not." (PMID 26033355, 2015). "Although the HGF/c-Met pathway is well recognized for its role in regeneration of AECs in humans, little is known about HGF/c-Met signaling in the innate immune response during respiratory infections including influenza infection." (PMID 26033355, 2015). "As observed, Influenza induces IL-8 and granulocyte–macrophage colony-stimulating factor (GM-CSF) secretion by human alveolar epithelial cells through recombinant human Hepatocyte growth factor (HGF)/c-Met and TGF-α/ epidermal growth factor receptor (EGFR) signaling." (PMID 40164948, 2025). "Therefore, we hypothesized that HGF secreted by FBs would stimulate IL-8 and GM-CSF secretion by AECs during influenza infection." (PMID 26033355, 2015). "AECs infected with influenza secreted PGE2, and exogenous PGE2 stimulated secretion of HGF by human lung FBs." (PMID 26033355, 2015). "The other pathway involved the stimulation of c-Met on AECs by HGF, which was produced by FBs stimulated by PGE2 produced by AECs infected with influenza." (PMID 26033355, 2015). "In this report, we studied cytokine/chemokine induction by recombinant human HGF (rhHGF) and rhTGF-α in human AECs and activation of c-Met and EGFR signaling in AECs during influenza infection." (PMID 26033355, 2015). "We conclude that HGF/c-Met and TGF-α/EGFR signaling enhances the innate immune responses by human AECs during influenza infections." (PMID 26033355, 2015). "Influenza infection stimulated the secretion of IL-8 and GM-CSF by AECs plated on rat-tail collagen through EGFR activation likely by TGF-α released from AECs and through c-Met activated by HGF secreted from lung fibroblasts." (PMID 26033355, 2015). "As c-Met ligand, HGF, is strongly expressed by lung FBs but not by human AECs, we examined the effect of HGF/c-Met signaling on IL-8 secretion by AECs during influenza infection using a coculture system of AECs with FBs." (PMID 26033355, 2015).
kidney cancer (5 papers, 2019 to 2023). Primary or metastatic malignant neoplasm involving the kidney. "FPMXY-14 dose-dependently inhibited the endothelial trans-migration of both the kidney cancer cells across the HUVEC cell membrane under the influence of an HGF." (PMID 37304673, 2021). "Among these 26 kidney cancer genes, HGF which is the ligand of c-met was predicted to be connected in this network." (PMID 31575031, 2019). "Indeed, several inhibitors of the HGFR/HGF pathway were analyzed in different cancer entities including lung, liver and kidney cancer." (PMID 36359213, 2022). "The dysregulation of MET, another tyrosine kinase receptor activated by the hepatocyte growth factor (HGF), induces the activation of both the PI3K-Akt and Ras/MAPK pathways which promote cell growth and metastasis in kidney cancer." (PMID 35892875, 2022).
kidney damage (5 papers, 2017 to 2024). "β-catenin is subsequently released and translocated into the nucleus in response to Wnt/β-catenin signaling activation, and the expression of HGF is repressed, leading to severe kidney damage." (PMID 38710691, 2024). "That being said, there is evidence that elevated HGF levels is correlated with the manifestation of renal dysfunction, manifested through nephropathy." (PMID 34829612, 2021). "Inflammatory cytokines, growth factors, and prostaglandin that are produced during kidney damage regulate the expression of HGF." (PMID 31728118, 2019). "In addition, in the drug‐induced AKI model, HGF administration improves the kidney damage and increases the survival rate, but the short half‐life of HGF produces the limitation that frequent administration is required." (PMID 32239661, 2020).
melasma (5 papers, 2015 to 2024). "It is the case of mice in which HGF over-expression causes aberrant myoblast and neural crest migration, leading to ectopic muscle formation and melanosis in the central nervous system." (PMID 26393505, 2015). "As it promote fibroblast proliferation and upper dermal collagenesis, microneedling can restore upper dermal and basal membrane damage in melasma, disfavouring the contact of melanocytes with dermal released melanogenic stimuli as endothelin, stem cell factor and hepatocyte growth factor." (PMID 29183309, 2017). "Since HGF and NGF are recognized melanogenic paracrine factors associated with solar lentigo and melasma pathogenesis, common hyperpigmentary skin disorders 52-55, the anti-melanogenic activity of altiratinib could potentially be mediated by interfering with these signaling pathways." (PMID 34815795, 2021). "Similarly, ET-1 in SL, HGF in DF /SL, KGF in SL /melasma, IL-1α in SL, sFRP-2 in SL /melasma, and NGF in melasma stimulate melanogenesis of human melanocytes." (PMID 38674144, 2024).
nasopharyngeal carcinoma (5 papers, 2011 to 2022). A carcinoma arising from the nasopharyngeal epithelium. "Hepatocyte growth factor-activated both Akt and JNK enhance the proteolysis and invasiveness of human nasopharyngeal cancer cells." (PMID 21859479, 2011).
pancreatic adenocarcinoma (5 papers, 2015 to 2021). "Therefore, HGF makes a potent novel target for developing therapeutic strategies in combination with existing drugs for treating pancreatic adenocarcinoma." (PMID 26404380, 2015). "report that DYRK1A is widely overexpressed among pancreatic adenocarcinomas, resulting in increased production of oncogenic hepatocyte growth factor, and that inhibition of DYRK1A by harmine attenuates the growth of pancreatic adenocarcinoma cells in vitro and in vivo." (PMID 34335466, 2021).
periodontal disease (5 papers, 2014 to 2025). "Elevated HGF concentrations have a convincing role as a marker of chronic inflammation including periodontal disease as patients with severe PD have higher HGF concentrations in gingival crevicular fluid (GCF), saliva, and serum." (PMID 29190740, 2017). "Thus, HGF might contribute to the development of periodontal disease in PD patients." (PMID 31382656, 2019).